NOTCH1 (notch receptor 1)
Diseases named in the same sentence as NOTCH1 in open-access papers (continued):
Sharing a sentence is not in itself a finding about the gene and the disease.
neurodevelopmental disorder (2 papers, 2021 to 2026). A behavioral and cognitive disorder with onset during the developmental period that involves impaired or aberrant development of intellectual, motor, or social functions. "A recent study indicates that the lack of NF-κB p50 subunit, via dysregulation of other key neurodevelopmental pathways, such as NOTCH1, is associated with neurodevelopmental disorders." (PMID 33917855, 2021). "Comparison of the NOTCH1 global DNAm profile with other neurodevelopmental disorders included in the EpiSign V5 classifier." (PMID 41501857, 2026).
gastrointestinal disease (1 paper, 2020). A disease that occurs in the gastrointestinal system, excluding the hepatobiliary system. "Taken together, the occurrence of H. pylori infection is accompanied by activated Notch1 and elevated expression of T-bet, indicating that Notch1 is a crucial mediator of Th1-mediated pathology in H. pylori–associated gastrointestinal disease through direct regulation of T-bet." (PMID 33224898, 2020).
NOTCH1 also shares sentences with these, for which no sentence is quoted: type 2 diabetes (9 papers); acute kidney injury (5); blood cancer (4); Hypercholesterolemia (4); pulmonary stenosis (4); Arrhythmia (3); calcific (3); chronic obstructive pulmonary disease (3); idiopathic pulmonary fibrosis (3); Kabuki syndrome (3); meningioma (3); psychiatric disorder (3); sarcoma (3); spinal cord injury (3); Wilms tumor (3); 22q11.2 deletion syndrome (2); acute myocardial infarction (2); allergic rhinitis (2); anaplastic astrocytoma (2); anaplastic oligodendroglioma (2); atrial fibrillation (2); autoimmune disorder (2); basaloid squamous cell carcinoma (2); chronic superficial gastritis (2); diseases of the endometrium (2); eosinophilia (2); Glomerular sclerosis (2); infarction (2); inflammatory bowel disease (2); Intellectual disability (2).
A further 187 diseases each share a sentence with NOTCH1 in 2 papers or fewer.